BRCA1 (BRCA1 DNA repair associated)
Diseases named in the same sentence as BRCA1 in open-access papers (continued):
Sharing a sentence is not in itself a finding about the gene and the disease.
pancreatic cancer (continued). "Six cases of BRCA1/BRCA2 double heterozygotes were diagnosed with cancers outside of the usual spectrum of breast, ovarian, prostate and pancreatic cancers; three had colorectal cancer, one with gastric cancer, one with endometrial cancer and another with cervical cancer." (PMID 39843919, 2025). "Next, we investigated the mechanism by which OFD1 regulates BRCA1 transcription, GSEA molecular signatures analysis in OFD1 knockdown pancreatic cancer cells revealed significant enrichment of genes regulated by the DREAM complex in both PANC1 and MIA PaCa-2 cells upon OFD1 knockdown." (PMID 40764600, 2025). "Until now, no molecular-targeted agents have been approved for pancreatic cancer treatment, except poly ADP ribose polymerase (PARP) inhibitors, which are effective for pancreatic cancer with BRCA1/2 germline mutations." (PMID 37956396, 2024). "In BRCA1-proficient cells, for instance, the activity of BCRP and MRP1/2 decreased, whereas a strong increase in ABCA8 transcription was observed, which has already been described in the context of MDR in pancreatic cancer." (PMID 37568590, 2023). "For instance, PARP inhibitors have approval for use in patients with BRCA1/2 alterations in ovarian, prostate, breast, and pancreatic cancer; however, there is no pan‐cancer BRCA1/2 approval for these agents." (PMID 37712677, 2023). "Pancreatic cancer is another common BRCA-associated cancer; however, multiple studies have shown that BRCA2, but not BRCA1, predisposes individuals to pancreatic cancer." (PMID 36861435, 2023). "The incidences of pancreatic cancer in male relatives of BRCA1 carriers, BRCA2 carriers, and non-carriers were 1.4%, 2.7%, and 0.6%, respectively." (PMID 36861435, 2023). "For non-cancer individuals, carriers of a BRCA1 or BRCA2 pathogenic variants was recommended to take more intensive screening and preventive strategies for breast, ovarian, prostate and pancreatic cancer." (PMID 38274092, 2023). "Our data are limited to BC and do not extend to other BRCA1-related cancers such as ovarian, prostate, or pancreatic cancer." (PMID 36223740, 2022). "For example, the DDR genes BRCA1, BRCA2 and ATM, or PALB2, each one usually found mutated in no more than 3.5% of cases, increase pancreatic cancer risk when altered at the germline level." (PMID 35563100, 2022). "The risk for pancreatic cancer in individuals with pathogenic variants of BRCA1, BRCA2, PALB2, or ATM but without a history of pancreatic cancer has not been elucidated." (PMID 35163129, 2022). "Further, BRCA1, BRCA2 and PALB2 mutant pancreatic cancer frequently shows signature 3, and the presence of signature 3 is predictive of response to platinum chemotherapy in patients with advanced pancreatic cancer." (PMID 34572943, 2021). "Thus, we expected chromosomal instability and hypersensitivity of primary tumor cells isolated from Palb2-KPC, Brca1-KPC, or Brca2-KPC pancreatic tumors to DNA damaging agents." (PMID 31877165, 2019). "Interestingly, PRRX1 could transcriptionally maintain the expressions of DDR genes including ATM, ATR, BRCA1, PRKDC, and XRCC1, in PANC1 pancreatic cancer cells." (PMID 40114375, 2025). "Consequently, BRCA1 and BRCA2 emerge as the predominant contributors to familial pancreatic cancer." (PMID 38809921, 2024). "The role of polymerase theta inhibition in pancreatic cancers with BRCA1/BRCA2 and non-BRCA HR defects and possibly defects in other repair pathways could be the logical step for investigation in future trials." (PMID 36975505, 2023). "Thus, most pancreatic cancer patients with normal BRCA1/2 function are not eligible to receive PARP inhibitors." (PMID 37415733, 2023). "Our analysis of pancreatic cancer patients did not detect any effects of BRCA1/2m on OS." (PMID 35909902, 2022).
pancreatic cancer (continued). "However, recent data have sparked debate over just how predictive BRCA1/2-mutated cancers can be to PARPis, especially in non-BRCA-associated cancer types (cancers not including breast, ovary, prostate, or pancreatic cancer)." (PMID 33233320, 2020). "Of the 64 pancreatic cancer samples where it was possible to obtain a result, one (1.6%) individual carrying the BRCA2 c.156_157insAlu mutation was identified and none was a carrier of the BRCA1 c.3331_3334del mutation." (PMID 27532258, 2016). "Retrospective multicenter studies with large BRCA1 and BRCA2 patient cohorts and prospective studies reviewing serial follow-up imaging on such patients are needed to further assess the potential benefits of modification to current pancreatic cancer screening guidelines." (PMID 27069714, 2016). "Although the other variants in BRCA1, ATM, and POLQ were not previously reported and were identified as novel variants in this current study, pathogenic variants in these genes have also been reported in pancreatic cancer and therefore these genes have been known to cause PDAC." (PMID 37234870, 2023). "Human pancreatic cancer cells lines (BxPC-3, CFPAC-1) were exposed to 0.5μM pimasertib under hypoxia (3% 02) for 4 hours and downregulation of BRCA2 protein expression was observed upon MEK inhibition whereas BRCA1 expression was unaffected (data not shown)." (PMID 29545922, 2018).
serous ovarian cancer (255 papers, 2008 to 2026). "Patients with high-grade serous ovarian carcinoma (HGSOC) with BRCA1/2 mutations show homologous recombination (HR) deficiency (HRD) and poly (ADP-ribose) polymerase inhibitors (PARPi) sensitivity." (PMID 41417832, 2026). "In high-grade serous ovarian cancer, this vulnerability is often driven by defects in homologous recombination (HR), such as BRCA1/2 mutations, or BRCA reversion mutations that confer PARPi resistance." (PMID 41409249, 2025). "This included a patient with stage IIIC high-grade serous ovarian cancer with germline BRCA1 p.D96E mutation and Sig3 positivity who benefited from treatment with a PARP inhibitor." (PMID 40570257, 2025). "BRCA2-associated high-grade serous ovarian carcinomas (HGSOCs) demonstrated significantly higher rates of pathologic complete response (pCR) as compared to BRCA1-related cancers [8/15 (53%) vs. 7/48 (15%), P = 0.004]." (PMID 40547808, 2025). "The literature does show that OC in women with a BRCA1 or BRCA2 GPV is generally associated with high-grade serous ovarian carcinoma." (PMID 40428378, 2025). "A Slovakian study performed MLPA analyses in 39 tumor samples of high-grade serous ovarian cancer and detected one pathogenic BRCA1 deletion (2.6%)." (PMID 38730634, 2024). "Several studies in serous ovarian cancer highlight the prognostic and predictive roles of BRCA1 and BRCA2 germlines and somatic mutations in survival and responses to platinum-based treatments." (PMID 39199616, 2024). "Researchers have tried to draw an analogy between the endometrial carcinoma, mainly the serous subtype, and the serous ovarian carcinoma, the latter being well known for its association with a positive family history and germline mutations in BRCA1/2." (PMID 39061183, 2024). "In patients with high-grade serous ovarian cancer, a BRCA1 or BRCA2 mutation was found in 22% of tumors." (PMID 37760950, 2023). "High-grade serous ovarian cancer (HGSOC) patients carrying the BRCA1/2 mutation or deficient in the homologous recombination repair system (HRD) generally benefit from treatment with PARP inhibitors." (PMID 38069422, 2023). "The PARP inhibitor (PARPi) olaparib is currently the drug of choice for serous ovarian cancer (OC), especially in patients with homologous recombination (HR) repair deficiency associated with deleterious BRCA1/2 mutations." (PMID 37048111, 2023). "HUWE1 catalytic domain mutations were also seen in a case of PARPi resistant, BRCA1 exon 11 mutant, high grade serous ovarian cancer." (PMID 37491606, 2023). "The assay was established using high-grade serous ovarian cancer samples for which BRCA1 and BRCA2 mutation status as well as Myriad MyChoice homologous repair deficiency (HRD) status was known." (PMID 37444554, 2023). "•7% somatic BRCA1/2 pathogenic variant (PV) rate in older high-grade serous ovarian carcinoma (HGSC) patients." (PMID 36805919, 2023). "The profiles of epithelial carcinomas, including ovarian serous carcinomas and CCCs, and NETs, which are rare, were compared for chemoresistance, BRCA1/2 mutations, and HRD, which affect the efficacy of PARP inhibitors." (PMID 35676859, 2023). "The most prevalent mutation, BRCA1 c.3607C>T, which is less common in the Romanian population, was mainly associated with triple-negative BC and ovarian serous adenocarcinoma." (PMID 35409996, 2022). "BRCA1 and BRCA2 play crucial roles in DNA double-strand break repair by homologous recombination, and prevalence of BRCA1/2 mutation in patients with newly diagnosed high-grade serous ovarian cancer is 20-25% (2011,)." (PMID 35466318, 2022). "BRCA1 is frequently methylated in high-grade serous ovarian cancer (HGSOC) and can lead to HR-deficiency (HRD) which is associated with increased patient survival following platinum-based chemotherapy compared to patients with HR proficient tumours." (PMID 35326684, 2022).
serous ovarian cancer (continued). "Germline BRCA1/2 mutations are found in approximately 18% of high grade serous ovarian cancer (HGSOC) patients, while exclusive somatic mutations in BRCA1/2 occur in about 3–8%." (PMID 36143252, 2022). "Despite recent advances in the management of BRCA1 mutated high-grade serous ovarian cancer (HGSC), the physiology of these tumors remains poorly understood." (PMID 35292711, 2022). "The majority of high-grade serous ovarian cancers (HGSCs) are deficient in homologous recombination (HR) DNA repair, most commonly due to mutations or hypermethylation of the BRCA1/2 genes." (PMID 35149709, 2022). "Treatment with PARP inhibitors (PARPi) is primarily effective against high-grade serous ovarian cancers (HGSOC) with BRCA1/2 mutations or other deficiencies in homologous recombination (HR) repair mechanisms." (PMID 35964058, 2022). "The aim of this single-center, observational, retrospective study was to explore the relationship between hormone receptor status and BRCA1/2 mutation in a cohort of 207 high-grade serous ovarian carcinoma (HGSOC) patients." (PMID 36230510, 2022). "BRCA1/2 mutations are common in Taiwanese patients with serous ovarian carcinoma, and similar mutation rates are observed in other ethnic groups." (PMID 36233495, 2022). "UWB cells from a high grade serous ovarian carcinoma carry a germline BRCA1 pathogenic variant within exon 11 and have a deletion of the WT allele, and the UWB+B cell line had previously been generated from parental UWB cells by stable transfection." (PMID 36183837, 2022). "Specifically, results of previous studies suggest that patients with high grade serous ovarian cancer and either BRCA1 or BRCA2 mutations have different clinicopathological features, response to treatment, and prognosis." (PMID 34898566, 2021). "To date, little is known about the clinical impact of differently mutated BRCA1/BRCA2 domains on high grade serous ovarian cancer prognosis." (PMID 34898566, 2021). "The presence of somatic or germline BRCA1/2 pathogenic variants impacts the effectiveness of PARP inhibitor therapy in high‐grade serous ovarian cancer." (PMID 33030818, 2021). "The association between cyclin E gene amplification and BRCA1/2 mutations have been examined previously and in studies with high grade serous ovarian cancer, such associations were found to be mutually exclusive." (PMID 33916118, 2021). "Women who carry genetic variants in BRCA1/2 that are linked to high‐grade serous ovarian cancer are advised to undergo risk‐reducing prophylactic bilateral salpingo‐oophorectomy (RRBSO)." (PMID 33152107, 2021). "Loss of BRCA1 function has also been documented through its promoter methylation in about 10% of high grade serous ovarian cancer (HGSOC) patients." (PMID 34195090, 2021). "PARP inhibitors are emerging as a promising maintenance treatment for high-grade serous ovarian cancers (HGSOCs) with germline or somatic BRCA1/2 mutations." (PMID 34461858, 2021). "In a cohort of 53 patients with serous ovarian cancer (29 BRCA1-mutated, 8 BRCA2-mutated, 16 HR-proficient), BRCA-mutated tumors exhibited increased CD3+ and CD8+ T cells as compared to HR-proficient tumors." (PMID 34067105, 2021). "Here, the rate of PPC following prophylactic surgery for high‐grade serous ovarian cancer was investigated among 2,193 BRCA1/2 mutation carriers who had undergone RRBSO." (PMID 33152107, 2021). "Germline pathogenic mutations in BReast CAncer (BRCA1) genes are thought to drive normal fallopian tube epithelial (FTE) cell transformation to high-grade serous ovarian cancer." (PMID 34965417, 2021). "The benefit of PARP inhibitor olaparib in relapsed and advanced high-grade serous ovarian carcinoma (HGSOC) is well established especially in BRCA1/2 mutation carriers." (PMID 33803939, 2021).
serous ovarian cancer (continued). "Fifty-one patients with high grade serous ovarian carcinoma that bared germline mutations in the BRCA1/2 genes were included in this study." (PMID 34898566, 2021). "Poly (ADP-ribose) polymerase inhibitors targeting BRCA1/2 mutations are available for treating patients with high-grade serous ovarian cancer." (PMID 32164585, 2020). "In the case of serous ovarian cancers, up to 25% of cases contain germline mutations with the most common being BRCA1 or BRCA2 mutations." (PMID 32098452, 2020). "Cancer tissue from 98 patients with high-grade serous ovarian cancer who underwent Sanger sequencing for germline BRCA1/2 analysis were consecutively analyzed for somatic mutations using a next-generation sequencing 170-gene panel." (PMID 32164585, 2020). "The study has pointed out that serous ovarian cancer was sensitive to platinum because of a functional defect caused by insufficient BRCA1 levels." (PMID 32762026, 2020). "Approximately 50% of high-grade serous ovarian cancers are characterized by HR deficiency, which involves mutations in BRCA1/2, the MRN complex (MRE11, RAD50, NBS1), ATM, RAD51C/D, PALB2, BRIP1, BARD1, and other genes." (PMID 31572446, 2019). "While the cause of such methylation is poorly understood, mosaic normal tissue BRCA1 methylation is associated with a 2-3 fold increased risk of high-grade serous ovarian cancer (HGSOC)." (PMID 31225507, 2019). "The proband was a patient with high-grade serous ovarian cancer (HGSOC) who was found to harbor a pathogenic BRCA1 variant." (PMID 31516641, 2019). "High-grade serous ovarian cancer is the cancer subtype for which germline BRCA1/2 mutations are detected at the highest frequency with 8-15% carrying a BRCA1 and 4-8% a BRCA2 mutation." (PMID 31225507, 2019). "Reduced BRCA1 expression causes homologous recombination (HR) repair defects in high-grade serous ovarian cancers (HGSOCs)." (PMID 31604914, 2019). "Somatic BRCA1 mutations have been identified as a significant feature of high grade serous ovarian carcinoma." (PMID 30786925, 2019). "Reversion of BRCA1/2 germline mutations was assessed in ctDNA for 30 patients with high grade serous ovarian carcinoma." (PMID 31167492, 2019). "In the high-grade ovarian serous carcinoma subgroup, 31.4% of cases harbored a clinically significant mutation (n = 61 cases, 47 BRCA1 and n = 14 BRCA2), whereas only one likely pathogenic BRCA2 alteration was detected in non-high-grade serous carcinoma." (PMID 31653094, 2019). "Patients with BRCA1/2 germline mutated serous ovarian cancers responded better to first-line chemotherapy in the metastatic setting in comparison with sporadic serous high-grade carcinomas." (PMID 29453630, 2018). "Irrespective of family history, 17% of women aged 70 years or younger with newly diagnosed high grade serous ovarian cancer (HGSOC) harbor a germline BRCA1/2 pathologic variant." (PMID 29344385, 2018). "The finding in our manuscript that 21.3% of serous ovarian cancer patients were germline BRCA1 or BRCA2 mutation carriers is consistent with previous research reporting a 20% and 23% germline mutation rate in HGSC patients." (PMID 29506471, 2018). "These trials predominantly enrolled women with high-grade serous ovarian carcinoma and a germline BRCA1/2 mutation (gBRCAmt)." (PMID 29464354, 2018). "It has been estimated that nearly half of high-grade serous ovarian cancers have germ line or somatic mutations in BRCA1 or BRCA2." (PMID 29254281, 2017).